MMP9 (matrix metallopeptidase 9)
Diseases named in the same sentence as MMP9 in open-access papers (continued):
Sharing a sentence is not in itself a finding about the gene and the disease.
glioma (continued). "Higher expression levels of HOXC6, MMP9 and SHOX2, and lower expression levels of MYOD1 were observed in the glioma tissues with promoter-unmethylation of MGMT in TCGA." (PMID 36118887, 2022). "In the presence of glioma cells, microglia produce significant amounts of TGF-β, which in turn induces production of matrix metalloproteinase 9 (MMP9) and MMP2, leading to degradation of ECM and supporting glioma stem cell invasion." (PMID 36776369, 2022). "Slc39a1 is a zinc ion transport protein related to the progression of glioma by promoting MMP2 and MMP9, and is increased in the progression of schizophrenia." (PMID 36614117, 2022). "Tissue invasion and metastasis, which includes glioma invasiveness signaling with the up-regulation of CD44 and matrix metalloproteinase 9 (MMP9), was activated after 6 h of treatment with TPA." (PMID 35328637, 2022). "In the present study, through perform IHC, we found that high expression of HOXC6, MMP9 and SHOX2 and low expression of MYOD1 were observed in recurrent glioma tissues." (PMID 36118887, 2022). "In gliomas, CTSB can bind to ANXA2 and induce the expression of vascular endothelial growth factor C, TGF-β, and MMP9 to promote angiogenesis." (PMID 36076905, 2022). "In this study, the role of MUC4, MMP9, and EGFR in the progression and clinical outcome of glioma patients was investigated." (PMID 36400876, 2022). "Lack of ST8SIA1 expression resulted in the prolonged lifespan of glioma-bearing mice, and low-grade pathology in generated gliomas, by modulating the AP2/MMP9 axis." (PMID 35267607, 2022). "Interesting, in the current study, we found that HOXC6, MMP9 and SHOX2 expression were increased in the glioma tissues with promoter unmethylation of MGMT, while MYOD1 was reduced." (PMID 36118887, 2022). "And some researchers found that the mechanism of MMP14 in glioma mainly works by cutting CD44, or via the combination of TIMP-2 and MMP14 to activate MMP-2 and MMP9 to enhance tumor invasion and tumor cell proliferation." (PMID 34712139, 2021). "An antibiotic, minocycline, significantly reduced MMP-9 production and TLR-2 expression in microglial cells treated with glioma conditioned medium." (PMID 34439380, 2021). "Our study found that HNRNPD was highly expressed in glioma tissues and cells, knockdown of HNRNPD significantly reduced the expression of MMP2, MMP9, and VE-cadherin in U87 and U251 cells, further inhibited the VM formation." (PMID 33542193, 2021). "Collectively, these data suggest that fraxetin had an inhibitory effect on the migration and invasion of glioma cells via downregulating MMP-2 and MMP-9." (PMID 33959183, 2021). "Initially, we explored the mRNA expression of MMP2, MMP9 and MMP14 in the human glioma cell lines T98G, U87MG, U138MG, U251MG and A172 by real time RT-qPCR." (PMID 33919029, 2021). "Glioma migration and invasion were also reduced after ectopic expression of BMAL1, leading to downregulation of p-AKT and MMP-9 signaling pathways." (PMID 34361055, 2021). "The Notch /JAG1 signaling pathway can work directly with other essential pathways such as MMP9 and VEGF to regulate glioma growth and malignancy, which defines patients’ physical condition with glioma." (PMID 36643842, 2021). "The results revealed that knockdown of TROAP drastically downregulated the level of MMP2, MMP7, MMP9, RHOA, RHOA, ROCK1 protein in U251 glioma cell lines compared to control group (p < 0.05)." (PMID 34077623, 2021). "Taken together, the results suggest that NE increases the expression of CD147 by activating the ERK signalling pathway in glioma cells and then induces the expression of MMP‐2 and MMP‐9 to promote tumour invasion." (PMID 34169637, 2021). "Further mechanistic studies indicated that mangiferin inhibits MMP‐9 by the inhibition of the binding of NF‐κB and AP‐1 to MMP‐9 promoters to block glioma invasion and angiogenesis." (PMID 33300633, 2021).
glioma (continued). "In this study, we found out that fraxetin inhibits the invasion and migration of glioma by downregulating the expression of MMP-2 and MMP-9 in a dose-dependent manner." (PMID 33959183, 2021). "In glioma, increased EFEMP1expression promotes tumor invasion and progression by modulating the extracellular matrix by increasing the expression of MMP2, MMP9 and ADAMTS-5 via Notch signaling." (PMID 34204134, 2021). "We also performed ELISA detection and found that BATF2 upregulation significantly decreased VEGFA, MMP2, and MMP-9 levels in glioma tissues (VEGFA: p < 0.001; MMP2: p < 0.01; MMP-9: p < 0.01) and exhibited decreased MMP-9 staining in U251-BATF2 tumour." (PMID 33452462, 2021). "EN2 is under-expressed in gliomas, and elevated EN2 expression restrains cell multiplication, enhances tumor sensitivity to temozolomide, and blocks tumor cell invasion by repressing MMP9 expression." (PMID 33685351, 2021). "Pam3CSK4 increased the migratory and invasive capability of GSCs by enhancing MMP-2 and MMP-9 expression, while TLR2 knockout attenuated the effects and prolonged survival in glioma mouse model." (PMID 34715891, 2021). "We found that the following neutrophil chemokines—MMP9, CCL2, CCL5, CXCR4, CXCR2, CCL23, and IL8 (p = 0.07)—were enriched in TERTmut gliomas (t-test, p < 0.05)." (PMID 33996815, 2021). "miRNAs regulate cancer cell biology including cell proliferation and invasion in glioma and ovarian cancer cells via HIF-1α and MMP9 pathways." (PMID 33919449, 2021). "We show that UII treatment of GBM xenografts evoked MMP-2 and MMP-9 overexpression mainly in the vascular and glioma cell compartments, respectively, and that UII stimulates MMP9 gene expression in hCMEC/D3 in vitro." (PMID 33937253, 2021). "For example, glioma cells can increase their expression of CD44, the main surface receptor for HA that also binds to matrix metalloproteinase 9 (MMP9) found in the ECM." (PMID 34571905, 2021). "MMP-2 and/or MMP-9 are upregulated by microglia in disorders where PNN breakdown occurs, such as stroke, multiple sclerosis, and glioma, and pharmacological MMP blockade in glioma ameliorates enhanced MMP-2/9 activity and associated PNN loss." (PMID 34413489, 2021). "It promotes the invasion of gliomas through upregulation of the expression of matrix metalloproteinase-7 (MMP-7), matrix metalloproteinase-9 (MMP-9), and vascular endothelial growth factor (VEGF)." (PMID 32650527, 2020). "The relationship between the presence of miRNA and the activity of metalloproteinases (MMP2, MMP3, MMP9, MMP12, MMP13, ADAM9) was demonstrated in many other observations conducted on gliomas, including glioblastoma." (PMID 32349263, 2020). "The role of some of them (MMP-2, MMP-9, MMP-14) has been proved in the process of developing high grade gliomas." (PMID 32349263, 2020). "In vitro experimental results show that SLC39A1 promotes proliferation of glioma cells, inhibits their apoptosis, and promotes expression of MMP2\MMP9." (PMID 33292262, 2020). "To date, several circRNAs have been reported to play crucial roles in gliomas, such as circ-SMARCA5, circ-MMP9, circ-NT5E, circ-TTBK2, and circ-LINC-PINT." (PMID 31905344, 2020). "To further investigate the effect of psychological stress on the invasion potential of glioma cells, we examined the expression and secretion of MMP-2 and MMP-9." (PMID 33178600, 2020). "In the meantime, we used a CCK-8, flow cytometer, RT-qPCR, western blot, and other technologies to analyze the correlation between SLC39A1 and glioma proliferation and apoptosis in vitro, and the expression of invasion-related MMP2\MMP9 proteins." (PMID 33292262, 2020). "Transfection of RIOK2 siRNAs significantly inhibited glioma cell migration and invasion and down‐regulated the expression of MMPs (MMP2 and MMP9) and mesenchymal markers (N‐cadherin, β‐catenin, Twist1, fibronectin, ZEB‐1) in glioma cells." (PMID 32125767, 2020).
glioma (continued). "FOXD2-AS1 promoted glioma proliferation, invasiveness and EMT by acting as a ceRNA to sponge miR-506-5p, thus regulating the protein levels of MMP7, MMP9, N-cad, E-cad and vimentin." (PMID 33336050, 2020). "It has been shown that the activity of certain matrix metalloproteases, such as MMP-2 (gelatinase A), MMP-9 (gelatinase B), MMP-14 (matrix metalloproteinase 14) is related to the pathophysiology of high-grade gliomas." (PMID 31661771, 2019). "ANXA2P2 was positively correlated with genes that are related to glioma proliferation, invasion and angiogenesis, such as ANXA2, CD44, IL6, MMP14, MMP9, and VEGFA." (PMID 31681595, 2019). "We evidenced that Cmp5 notably reduces glioma cell migration via the down-regulation of MMP-2 and MMP-9." (PMID 31130597, 2019). "Results derived from the study of glioma stem-like cells (GSLCs) indicated that their invasiveness is enhanced following the release of TGF-β1 from TAMs, which increases MMP9 expression." (PMID 31231208, 2019). "Forsyth investigated MMP-2, MMP-9, and MT1-MMPs’ function in the progression of glioma, in which MMP-9 was mainly participated in vascularization and remodeling." (PMID 31824776, 2019). "FOXM1 was shown to stimulate angiogenesis in several cancers, including pancreatic cancer, gastric cancer and glioma, through induction of vascular endothelial growth factor (VEGF), matrix metalloproteinase-2 (MMP-2) and MMP-9." (PMID 30486864, 2018). "As our results attribute peritumoral PNN degradation primarily to glioma-released MMPs (MMP-2, MMP-3, and MMP-9), we used a cocktail of these MMPs to degrade PNNs experimentally." (PMID 30413686, 2018). "Invasive gliomas show MMP2 and MMP9 overexpression and both MMP2 and MMP9 play important roles in infiltrative growth of gliomas." (PMID 30587839, 2018). "In gliomas, the cleavage of CD44 is important for tumor cell migration, invasion and adhesion and this is induced by matrix metalloproteinase-9 (MMP-9)." (PMID 29914429, 2018). "Both siPLP2 transfected gliomas showed a clear inhibition of glioma cell proliferation, migration, and invasion as well as down-regulating p-p38, p-ERK, MMP-2, and MMP-9 expression." (PMID 30373180, 2018). "Data obtained from our study indicated that conditioned medium from M2 cells (M2-CM) increased the tubule formation number in glioma cells, as well as VM marker expression, including LAMC2, MMP-9 and MMP-14." (PMID 27903982, 2017). "In glioma cells, MMP-2 and MMP-9 are highly expressed and are involved in GBM migration and invasion." (PMID 29062841, 2017). "The upregulated CLC-3 in gliomas promotes NF-κB transactivity to regulate intracellular transcriptomic plasticity, alters matrix metalloproteinase such as MMP-3, MMP-9 expression, and actively modulates the extracellular environment." (PMID 28969029, 2017). "Glioma cells secrete an array of proteases to be involved in glioma cell invasion, including MMP2 and MMP9, and the membrane-bound MMP, MT1-MMP (also known as MMP-14)." (PMID 29207533, 2017). "MMP-9 and MMP-2 degrade the extracellular matrix and result in the migration of glioma cells to other normal tissue area." (PMID 29062841, 2017). "Our data confirm that CBX7 inhibits EMT and invasion in glioma, which is manifested by influencing the expression of MMP2, MMP9, E-cadherin, N-cadherin and Vimentin in LN229, T98G cells and primary glioma cells (PGC)." (PMID 28388562, 2017). "SDC1 knockdown attenuated proliferation and invasion by glioma cells and markedly decreased PCNA and MMP-9 mRNA and protein expression." (PMID 28422726, 2017). "Giusti et colleagues showed, for example, which vesicles produced by glioma cells contain the MMP-2 gelatinase, both in pro-enzimatic and active form, as well as pro-MMP9." (PMID 29261132, 2017). "MMP-9 inhibitor SB-3CT and dexamethasone was used to inhibit Mycobacterium tuberculosis induced MMP-9 in C6 glioma cells." (PMID 27899068, 2016).
glioma (continued). "Expression of Ki67, MMP-9, Cyclin D1, Bcl-2 and C-myc was varied in accordance with the level of TAZ in glioma cell." (PMID 27764783, 2016). "The induction of MMP-2 and/or MMP-9 by Bcl-2 overexpression is mediated by AP-1 in lung cancer cells, furin and TGF-β in glioma cells, and the N-cadherin/FGF receptor/ERK pathway in squamous carcinoma cells." (PMID 26621844, 2016). "IL-6 has been reported to enhance tumor (including gliomas) migration and invasion through up-regulation or activation of MMP2 or MMP9." (PMID 27613828, 2016). "We recently reported the association between the baseline circulating MMP2 level and, to a lesser extent, the MMP9 level, and the response rate, PFS and OS of patients treated with bevacizumab for recurrent high-grade glioma." (PMID 26921265, 2016). "Increased levels of MMP-2 and 9 were observed in CSF of high-grade glioma patients, and a larger study confirmed increased plasma levels of MMP-9 and TIMP-1 in patients with both grade II and IV glioma compared to healthy controls." (PMID 25720744, 2015). "Despite the findings of elevated MMP-9/NGAL levels in brain tumors, little is known about the relationship between the activity of MMP-9/NGAL in glioma patient response and prognosis." (PMID 26663949, 2015). "In the present study, we firstly reported that GCN5 was frequently overexpressed in human glioma tissues and GCN5 was positively correlated with proliferation of cell nuclear antigen PCNA and matrix metallopeptidase MMP9." (PMID 26378521, 2015). "Up-regulation of miR-335 in glioma cells reduces expression of PAX6, thus promoting cell proliferation and is accompanied by increased protein levels of MMP-2 and MMP-9." (PMID 26204513, 2015). "In contrast, all four active MMPs, including MMP-9/NGAL, were detected in almost all glioma tissue (TT) and Preop-1d urine of glioma patients, consistent with previous findings." (PMID 26663949, 2015). "Previously, leptin was reported to be able to increase the expression of MMP-2, MMP-7 or MMP-9 in different cancer cells, as well as the expression of MMP-13 in glioma cells." (PMID 25948792, 2015). "To assess the relationship between MMP-9/NGAL activity and glioma disease status, we compared MMP-9/NGAL activity and the clinicopathological factors of our patient cohort." (PMID 26663949, 2015). "Several serum biomarkers-YKL40, MMP9, B-chain of α2-Heremans-Schmid glycoprotein (AHSG), Haptaglobin α2, Osteopontin and IGFBP2 have been reported to identify glioma." (PMID 26390214, 2015). "In a glioma cell line, gene silencing of HIF-1α can downregulate MMP-2/MMP-9 to suppress cell migration and invasion into adjacent normal tissue." (PMID 25816356, 2015). "Accordingly, very recently was demonstrated that SERPINE2 gene knockdown increased MMP-9 and MMP-2 expression in C6 glioma cell line." (PMID 26305372, 2015). "Elevated levels of MMP-2, MMP-9, MMP-9/NGAL, and some high molecular weight MMPs have been found in the urine, cerebrospinal fluid, and tumor tissue specimens from glioma patients." (PMID 26663949, 2015). "Here, we found elevated MMP-9, MMP-9/NGAL, and MMP-9 Dimer activity in both glioma tissues and preoperative urine from glioma patients compared to control subjects." (PMID 26663949, 2015). "This study demonstrates that urinary MMP-9/NGAL activity levels can predict disease status and prognosis in glioma patients." (PMID 26663949, 2015). "The invasive biomarkers of gliomas, MMP-2 and MMP-9, have also markedly positive correlation with TGFB1I1." (PMID 25333259, 2014). "For instance, SAA is able to induce the production of MMP-2 and MMP-3 in synovial fibroblasts, MMP-9 activity in monocytic cells and MMP-2 and 9 activity in glioma cell lines." (PMID 24614130, 2014). "Artemether reduces the migration and invasion capability of glioma cells and promotes the apoptosis of U87 human glioma cells by inhibiting MMP-2, MMP-9 and p-Akt expressions." (PMID 23593320, 2013).
glioma (continued). "The potential utility of MMP-9 as a biomarker in urine and CSF contrasts the results of a recent study investigating MMP-9’s role as a serum biomarker of gliomas." (PMID 24400253, 2013). "Another role in the production of MMP-9 in glioma cells is played by protein kinase C (PKC) and IL-6 is a confirmed growth factor for glioma stem cells, too." (PMID 24023566, 2013). "To understand the mechanism by which overexpression of Bmi-1 promoted the invasiveness and migration of glioma cells, we investigated the expression and activity of MMP-9 in A172 and LN229 glioma cells stably overexpressing Bmi-1." (PMID 22967049, 2012). "Ectopic expression of TIMP3 inhibited U251 and LN229 glioma cell invasion through the inhibition of MMP2 and MMP9 expression and activity." (PMID 22681957, 2012). "The culture supernatants of glioma cell lines were assayed for MMP-2 and MMP-9 gelatinase activities." (PMID 20587068, 2010). "In order to distinguish the role of heparanase on cell invasion, MMP-2 and MMP-9, members of the MMP family that is also involved in glioma invasion, was measured using zymography assay and real-time PCR in both heparanase-overexpressing and control cells." (PMID 18647407, 2008). "Elevated MMP-9 levels in the CSF of patients with recurrent glioma undergoing doxycycline treatment indicated a lack of therapeutic response." (PMID 40265458, 2025). "The authors conclude that serum MMP-9 does not provide any utility in determining glioma disease status and is not a clinically meaningful prognostic marker of survival." (PMID 40512281, 2025). "Indeed, simultaneous inhibition of MMP9 and CTSB, both downregulated in miR-7 overexpressed GBM tumors, has already been explored as a potential glioma treatment." (PMID 40813676, 2025). "Summing up, P129 could inhibit the invasion of glioma by suppressing MMP-2 and MMP-9 and EMT progression." (PMID 38184514, 2024). "Furthermore, a report on in vivo studies involving human glioma cells (U‐87) xenotransplant in mice revealed a property in curcumin to compress angiogenesis of glioma via suppressing CD105 and CD31 mRNA endothelial cell markers and MMP‐9." (PMID 39620006, 2024). "Intriguingly, previous findings have suggested differential expression patterns of MMP-9 and AQP4 in different grades of gliomas, and co-analysis of MMP-9 and AQP4 may help to identify tumour type and their progression stages." (PMID 39247976, 2024). "Overall, these data provide evidence that P129 could inhibit glioma cell metastasis via the downregulation of MMP-2 and MMP-9 and inhibition of EMT." (PMID 38184514, 2024). "In recent years, several studies have focused on quercetin’s effect on MMP-9, e.g., quercetin could inhibit the expression of MMP-9 via the AKT and ERK signalling pathways in gliomas." (PMID 37270490, 2023). "In addition, we found that the expression levels of VEGFA, MMP2, and MMP9 were, unsurprisingly, downregulated after inhibition of AKT signaling, even in L1‐overexpressing glioma cells." (PMID 36708044, 2023). "Serum MMP-9 showed no utility in determining glioma disease status and was not a clinically relevant prognostic marker of survival." (PMID 36765669, 2023). "Additionally, a study by Sarkar and Yong showed that increases in IL-1β and TNF-α levels were positively correlated with glioma cell invasiveness and a corresponding elevation of MMP-2 and MMP-9 proteins." (PMID 36675073, 2023). "Many interventions can inhibit glioma growth by inhibiting the expression of MMP-2 and MMP-9." (PMID 37759283, 2023). "Important factors expressed by TAMs in gliomas include TNF-ß, high levels of interleukins 6 and 10 (Il-6, Il-10), MMP2 and MMP9, and VEGF and VEGA, which collectively promote glioma proliferation and invasion, angiogenesis and suppression of T effector cell and NK cell activity." (PMID 38275375, 2023).